U3 (Small nucleolar RNA U3 )
Synonyms: LOC124904669
Gene: Small nucleolar RNA gene on chromosome 1 (116,278,606 to 116,278,821, forward strand). Ensembl gene ENSG00000221040.
Gene Ontology:
Biological process: RNA processing
Cellular component: nucleolus
Homologues: Orthologues: chimpanzee U3 (99% identical), macaque U3 (85% identical). Paralogues in human: U3 (75% identical), SNORD3P1 (74% identical), SNORD3G (72% identical), U3 (72% identical), SNORD3E (71% identical), U3 (71% identical), SNORD3D (70% identical), U3 (70% identical), U3 (69% identical), U3 (68% identical), U3 (67% identical), U3 (66% identical), and 11 more.